CYB5D2 (cytochrome b5 domain containing 2)
Description:
Heme-binding protein which promotes neuronal but not astrocyte differentiation.
Synonyms: MGC32124
Tractability: Antibody: UniProt places it where antibodies can reach, with medium confidence; UniProt predicts a signal peptide or a membrane-spanning region; its Gene Ontology location is reachable by antibodies, with medium confidence; the Human Protein Atlas places it where antibodies can reach. PROTAC: ubiquitination databases record sites on it; its protein half-life has been measured.
Gene: Protein-coding gene on chromosome 17 (4,143,168 to 4,187,310, forward strand). Ensembl gene ENSG00000167740.
Subcellular location: Secreted
Subcellular location (Human Protein Atlas): Endoplasmic reticulum; Plasma membrane; Predicted to be secreted
Gene Ontology:
Molecular function: protein binding; heme binding; steroid binding
Cellular component: extracellular region
Genetic constraint (gnomAD): Loss-of-function variants: 25 observed, 26.11 expected, observed/expected ratio (o/e) 0.96, 90% interval 0.7 to 1.34. The upper end of that interval is the gene's LOEUF score, 1.34, which puts it in group 5 of 6, group 1 being the genes least tolerant of losing a copy. Missense variants: 373 observed, 379.1 expected, observed/expected ratio (o/e) 0.98, 90% interval 0.9 to 1.07. Synonymous variants: 170 observed, 160.7 expected, observed/expected ratio (o/e) 1.06, 90% interval 0.93 to 1.2.
Homologues: Orthologues: chimpanzee CYB5D2 (99% identical), macaque CYB5D2 (96% identical), rabbit CYB5D2 (86% identical), pig CYB5D2 (81% identical), mouse Cyb5d2 (80% identical), dog CYB5D2 (80% identical), rat Cyb5d2 (80% identical), guinea pig CYB5D2 (80% identical), tropical clawed frog cyb5d2 (51% identical), zebrafish cyb5d2 (44% identical), Caenorhabditis elegans tag-131 (42% identical), Drosophila melanogaster CG12056 (36% identical). Paralogues in human: PGRMC1 (21% identical), PGRMC2 (19% identical), VMP1 (16% identical).
Diseases named in the same sentence as CYB5D2 in open-access papers:
CYB5D2 is named in the same sentence as 17 diseases in open-access papers, as found by Europe PMC text mining. Sharing a sentence is not in itself a finding about the gene and the disease. The quoted sentences say what the papers report.
breast carcinoma (5 papers, 2019 to 2025). "Researches have reported that decreased level of CYB5D2 is associated with breast cancer progression." (PMID 36881382, 2023). "We report here that CYB5D2 is associated with tumor suppression function in breast cancer (BC)." (PMID 31036830, 2019). "Extensive literature reviews indicate CYB5D2 exerts tumor-suppressive effects across multiple malignancies, including breast cancer, hepatocellular carcinoma, lung cancer, and clear cell renal cell carcinoma (ccRCC)." (PMID 40395557, 2025). "In breast cancer, CYB5D2 regulates mitosis, DNA metabolism, and repair processes to inhibit tumorigenesis." (PMID 40395557, 2025). "The downregulation of CYB5D2 has been found to facilitate breast cancer progression." (PMID 35865532, 2022).
cervical cancer (3 papers, 2016 to 2025). A primary or metastatic malignant neoplasm involving the cervix. "Postoperative survival data from cervical cancer patients were analyzed using Kaplan–Meier curves to examine the association between CYB5D2 protein expression and clinicopathological characteristics, as well as its prognostic implications." (PMID 40395557, 2025). "In conclusion, low CYB5D2 expression was identified as an independent risk factor for progression-free survival (PFS) in cervical cancer patients." (PMID 40395557, 2025). "Our ddPCR and immunohistochemistry data revealed that a progressive decrease in CYB5D2 expression with lesion severity, with 91.67% of cervical cancer tissues showing downregulation compared to chronic cervicitis." (PMID 40395557, 2025). "CYB5D2 expression was comprehensively assessed in 112 clinical samples, combined with routine cervical cancer screening methods to evaluate its early detection potential." (PMID 40395557, 2025). "Significant differences were observed in the expression of CYB5D2 among cervical cancer patients with varying FIGO stages, tumor size, myometrial infiltration, and differentiation degree." (PMID 40395557, 2025). "Recent studies implicate CYB5D2 (cytochrome B5 domain-containing protein 2), a tumor suppressor localized on chromosome 17p13, plays a role in cervical cancer development." (PMID 40395557, 2025). "To comprehensively elucidate the role of CYB5D2 in cervical cancer, we conducted a thorough analysis of data from the Gene Expression Omnibus (GEO) database." (PMID 40395557, 2025). "We have recently reported that CYB5D2 plays a role in suppression of cervical cancer tumorigenesis, “CYB5D2 displays tumor suppression activities towards cervical cancer”." (PMID 26937452, 2016). "Additionally, another study has shown that CYB5D2 contributes to the prevention of cervical cancer, and upregulation of this gene can prevent the malignant progression of human cervical cancer HeLa cells." (PMID 40109873, 2025). "Studies demonstrate CYB5D2 downregulation in cervical cancer, which may cooperate with HPV-induced microenvironmental changes to drive malignant transformation." (PMID 40395557, 2025). "Thus, changes in CYB5D2 expression could serve as a more precise biomarker for the diagnosis and staging of cervical cancer." (PMID 40395557, 2025). "Additionally, we analyzed CYB5D2 expression across different stages of cervical cancer." (PMID 40395557, 2025). "The relative fluorescence expression of CYB5D2 protein in normal cervical tissues, CIN tissues, and cervical cancer tissues was 91.38 ± 7.45, 58.06 ± 3.82, and 16.04 ± 3.60, respectively." (PMID 40395557, 2025). "Furthermore, we will present the conditions used to specifically determine CYB5D2 expression in primary cervical and cervical cancer tissues using immunohistochemistry (IHC) and the patient cohort involved in assessing the CYB5D2 protein levels in primary cervical and cervical cancer tissues." (PMID 26937452, 2016). "As cervical cancer progressed, there was a decrease in CYB5D2 expression which exhibited a negative correlation with patient PFS." (PMID 40395557, 2025).
hepatocellular carcinoma (2 papers, 2025). A malignant tumor that arises from hepatocytes. "In hepatocellular carcinoma, low CYB5D2 expression negatively correlates with TGF-β, and overexpression partially counteracts TGF-β-mediated cell proliferation and migration." (PMID 40395557, 2025).
acute lymphoblastic leukemia (1 paper, 2025). Leukemia with an acute onset, characterized by the presence of lymphoblasts in the bone marrow and the peripheral blood. "This aligns with prior reports that CYB5D2 as a tumor suppressor was detected in the gene spectrum of acute lymphoblastic leukemia." (PMID 40395557, 2025).
carcinoma in situ (1 paper, 2025). "In another study, CYB5D2 expression was found to decrease from carcinoma in situ (CIS) to SCC, suggesting an inverse correlation between CYB5D2 expression and tumor malignancy." (PMID 40395557, 2025).
cervical (1 paper, 2025). "Results revealed a progressive downregulation of CYB5D2 expression with advancing cervical lesions." (PMID 40395557, 2025).
Insulin resistance (1 paper, 2025). Increased resistance towards insulin, that is, diminished effectiveness of insulin in reducing blood glucose levels. "Additionally, a marginally significant SNP in chromosome 17 (rs11078484) for both liver fat and insulin resistance is coded for in the Cytochrome B5 Domain-Containing 2 gene (CYB5D2), which has been found to be correlated with diastolic blood pressure (DBP) and T2D." (PMID 40429953, 2025).
lymph node metastasis (1 paper, 2025). "Furthermore, the multivariate COX regression analysis revealed that FIGO stage III–IV confirmed by pathology during operation, presence of lymph node metastasis, and HPV16 infection were associated with poor prognosis along with low CYB5D2 expression." (PMID 40395557, 2025).
medulloblastoma (1 paper, 2020). A malignant, invasive embryonal neoplasm arising from the cerebellum. "Interestingly, the fraction of M2 macrophages in Group 4 medulloblastoma were positively correlated with the risk score and were significantly correlated with the expression level of four signature genes (CCNY, SYNE3, CYB5D2, and SELENOV) and four hub genes (GLI2, PAX6, RUNX2, and ZIC1)." (PMID 32508873, 2020).
neuroblastoma (1 paper, 2014). Neuroblastoma (NB) is the most common solid, extracranial childhood tumor. "It has recently been reported that murine CYB5D2 (Neuferricin) can be secreted from Neuro2a neuroblastoma cells, with Neuferricin knockdown promoting cell survival, proliferation and inhibiting neurite outgrowth." (PMID 24466094, 2014).
prostate carcinoma (1 paper, 2025). A carcinoma that arises from epithelial cells of the prostate gland. "Interestingly, in addition to genes linked to colorectal or prostate cancer, there were also two genes known to be associated with both of those cancer types: CYB5D2 and TRPM4." (PMID 41234971, 2025).
squamous intraepithelial lesions (1 paper, 2025). "Immunohistochemical detection of CYB5D2 protein outperformed ThinPrep cytology test (TCT), DNA aneuploidy analysis, and HR-HPV E6/E7 mRNA testing (mRNA expression of the E6 and E7 genes in high-risk HPV virus) in diagnosing high-grade squamous intraepithelial lesions (HSIL+) of the cervix." (PMID 40395557, 2025).
tumor (9 papers, 2014 to 2025). "Given the tumor-suppressive role of CYB5D2, its expression level is likely closely associated with patient prognosis." (PMID 40395557, 2025). "With the current knowledge, we suggest that CYB5D2 downregulation selectively associates with genomic alterations via CYB5D2-derived tumor suppression activity." (PMID 31036830, 2019). "These pathways are enriched in CYB5D2 downregulation-associated DEGs, supporting CYB5D2 as a novel tumor suppressor in BC." (PMID 31036830, 2019). "K-M curves showed that upregulated TRNP1, CCDC112, CFL1 were associated with poor OS) and CYB5D2, SLC22A1 were protective genes (expression of CYB5D2, SLC22A1 were decreased in tumor tissues, and higher expression of CYB5D2, SLC22A1 was associated with good OS)." (PMID 36881382, 2023). "Therefore, loss of heme-binding ability results in CYB5D2 “loss of function”, which seems to affect its putative tumor suppressor role." (PMID 24466094, 2014). "The purpose of this study was to investigate the involvement of TGF-β and CYB5D2 in tumor growth and HCC." (PMID 40109873, 2025). "In vivo, CYB5D2 overexpression significantly reduced tumor growth, indicating its potential as a therapeutic target for HCC." (PMID 40109873, 2025). "CYB5D2 expression was significantly lower in primary tumor samples compared to normal cervical tissues, indicating its potential role as a tumor suppressor." (PMID 40395557, 2025). "The tumor suppressor function of CYB5D2 in HCC and its interaction with TGF-β offered fresh information on the molecular pathophysiology of HCC and possible treatment avenues." (PMID 40109873, 2025). "This suggested that whilst TGF-β expression is markedly elevated in tumor tissues, CYB5D2 expression is low in malignant tissues." (PMID 40109873, 2025). "In vivo experiments further confirmed that CYB5D2 overexpression can significantly reduce tumor growth, indicating its potential application value as a therapeutic target for HCC." (PMID 40109873, 2025). "Among the genes significantly affected by ionizing radiation, we discovered BCL2L1, a gene involved in the regulation of apoptosis, and CYB5D2 that inhibits cell proliferation and has a putative tumor suppressor activity." (PMID 32883354, 2020). "CYB5D2 (cytochrome b5 domain containing 2) was reported as a new tumor suppressor in cervical cancer." (PMID 31036830, 2019). "As a result, these effects suggest that CYB5D2 functions as an inhibitor of cell proliferation, and further implicates that heme-binding is required for its putative tumor suppressor activity." (PMID 24466094, 2014). "CYB5D2 is a novel tumor suppressor gene that exhibits ectopic expression in various tumors." (PMID 40395557, 2025). "The heme-binding activity of CYB5D2 is closely related to oxidative stress, which may affect tumor invasion and metastasis by regulating the degradation of the extracellular matrix and cell motility." (PMID 40395557, 2025). "This pattern suggests that CYB5D2 may actively inhibit tumor progression in the early stages by suppressing the abnormal proliferation of tumor cells through multiple pathways." (PMID 40395557, 2025). "As the tumor progresses, tumor cells may develop mechanisms to suppress CYB5D2 expression or inactivate its function." (PMID 40395557, 2025). "In addition, tumor xenograft experiments also confirmed that CYB5D2 overexpression significantly inhibited tumor growth in mice." (PMID 40109873, 2025). "Collectively, we provide the first evidence that CYB5D2 is a candidate tumor suppressor of BC." (PMID 31036830, 2019). "To gain insight on the potential mechanisms contributing to the tumor suppression functions of CYB5D2 in BC, we analyzed pathways affected by the DEGs relative to CYB5D2 downregulation using the GAGE44 and Reactome45 packages in R as well as Ingenuity Pathway Analysis." (PMID 31036830, 2019).
tumor (continued). "This modulation of EMT-related factors corresponds to significant inhibition of HCC migration and invasion capabilities (the reduction in invasions may be attributed to factors such as reduced migration), supporting the theory that CYB5D2 could have tumor-suppressive effects in HCC." (PMID 40109873, 2025). "Overall, CYB5D2 plays an important role in the formation and progression of HCC and may have a significant impact on preventing EMT and tumor growth of HCC by regulating key EMT indicators and counteracting the tumorigenic effects of TGF-β." (PMID 40109873, 2025). "Among them, no staining signal was detected for CYB5D2 in tumor tissue, and TGF-β showed high staining intensity in tumor tissue." (PMID 40109873, 2025). "While the underlying mechanisms affecting the gene expression have not been studied, it is possible that CYB5D2 indirectly alters gene expression though its tumor suppression function." (PMID 31036830, 2019).
cancer (4 papers, 2014 to 2025). A tumor composed of atypical neoplastic, often pleomorphic cells that invade other tissues. "CYB5D2 was related to neurogenesis, neural functions, tumorigenesis, and cancer progression." (PMID 32508873, 2020). "Activation of ERK signaling, a prominent signaling pathway in cancer cells, remained unaffected following ectopic expression of CYBD2 or CYB5D2(D86G), and following CYB5D2 knockdown (data not shown)." (PMID 24466094, 2014).
CYB5D2 also shares sentences with these, for which no sentence is quoted: chronic cervicitis (1 paper); clear cell renal cell carcinoma (1); lung carcinoma (1).